MET (MET proto-oncogene, receptor tyrosine kinase)
Diseases named in the same sentence as MET in open-access papers (continued):
Sharing a sentence is not in itself a finding about the gene and the disease.
non-small cell lung carcinoma (continued). "Among them, a non-ATP competitive MET inhibitor, tivatinib (ARQ197), has been used in combination with erlotinib (EGFR-TKI) as second-line treatment for previously-treated non-small cell lung cancer." (PMID 27234388, 2013). "For mCRC, onartuzumab, a MET inhibitor, although phase II clinical trials have demonstrated its efficacy in combination with FOLFOX plus Bevacizumab, it is currently mainly used for non-small cell lung cancer (NSCLC) and has no further clinical trials related to gastrointestinal tumors." (PMID 41361128, 2025).
hepatocellular carcinoma (321 papers, 2003 to 2025). A malignant tumor that arises from hepatocytes. "Notable examples include circHGF, which encodes C-HGF to activate c-MET signaling and promote glioblastoma growth, and circZKSCAN1, which suppresses hepatocellular carcinoma through its interaction with FBXW7 and mTOR, thereby inhibiting the PI3K/AKT pathway." (PMID 40730815, 2025). "Heterozygous mutations in the MET gene have been described in lung adenocarcinoma, arthrogryposis, hepatocellular carcinoma, and papillary renal cell carcinoma (OMIM:164860)." (PMID 39886673, 2024). "Mutations in MET are associated with papillary renal cell carcinoma, hepatocellular carcinoma, and various head and neck cancers." (PMID 35975235, 2022). "MET mutations and amplification are associated with a variety of human cancers, such as papillary renal cell carcinoma and Hepatocellular carcinoma." (PMID 33190424, 2021). "Missense activating point mutations of MET were reported in papillary renal cell carcinoma, hepatocellular carcinoma, small-cell lung cancer and other cancers." (PMID 31040922, 2019). "For example, ALDH1A1 (stress response) and MAPK3 (cell proliferation) are targets of the HGF/MET signaling pathway which has been associated with tumor metastasis and poor prognosis in human hepatocellular carcinomas." (PMID 17900369, 2007). "MET codes for a receptor which is a transmembrane protein; its ligand is hepatocyte growth factor and mutations in the gene have been linked with development of hepatocellular carcinoma." (PMID 40489530, 2025). "In addition to NSCLC, research has indicated that the activation of the HGF/c-MET pathway is associated with increased PD-L1 expression in hepatocellular carcinoma following cisplatin treatment, downstream of the PI3K/Akt and MET/ERK pathways." (PMID 39201787, 2024). "Interestingly, MET mutations or alterations can be found in other cancers including hepatocellular carcinoma, endometrial, breast, gastric and squamous cell carcinoma of the head and neck." (PMID 36421797, 2022). "In addition, treatment of TANs with c-MET inhibitors reduced TAN associated hepatoma cell migration." (PMID 32117721, 2020). "Sustained activation of hepatocyte growth factor (HGF)/c-MET signaling is a major driver of hepatocellular carcinoma (HCC) progression, but underlying mechanism is unclear." (PMID 37061723, 2023). "First, we evaluated LL35 expression in a hepatocellular carcinoma (HCC) mouse model induced by plasmids encoding human ΔN90-β-catenin, human MET and Sleeping Beauty transposase." (PMID 35740417, 2022). "The vascular endothelial growth factor and c-MET pathways are strongly implicated in hepatocellular carcinoma (HCC)." (PMID 33919277, 2021). "Consistent with the upregulation of c-MET in ovarian and hepatocellular carcinoma cells by doxorubicin and sorafenib that may be linked to drug resistance, our data revealed higher levels of c-MET in OS cells treated with doxorubicin and sorafenib, alone or in combination." (PMID 28415566, 2017). "In hepatocellular carcinoma (HCC), previous studies have reported mutations in β-catenin, overexpression of receptors (such as ErbB and MET), chromosomal gains in 1q, 6p, 8q, 17q and 20q and chromosomal losses in 1p, 4q, 8p, 13q and 17p." (PMID 27895046, 2017). "Forced expression of miR-198 in hepatoma cells inhibits the expression of the signal transducer genes c-MET and CDK4, which promote proliferative pathways, and increases the expression of E-cadherin and claudin-1, which maintain cellular adhesion." (PMID 41465470, 2025). "Aberrant activation of MET has been shown to correlate with progression and poor prognosis in hepatocellular carcinoma." (PMID 39944086, 2025). "Specifically, miR-150 promotes NSCLC growth via SIRT2/JMJD2A activation, while miR-206 suppresses hepatocellular carcinoma by targeting c-MET." (PMID 41568382, 2025).
hepatocellular carcinoma (continued). "In hepatocellular carcinoma cells, overexpressed MET is retained in the Golgi/TGN region in a manner dependent on its tyrosine kinase activity." (PMID 40770227, 2025). "The HGF/c-MET signaling pathway plays a crucial role in cell proliferation, migration, invasion, and survival, with its dysregulation implicated in various cancers, including hepatocellular carcinoma (HCC)." (PMID 40867270, 2025). "The concomitant expression of c-MET and PD-L1 in tumors, such as hepatocellular carcinoma, highlights their prognostic significance and connection to therapeutic resistance." (PMID 39664377, 2024). "c-MET expression has been identified in hepatocellular carcinoma (HCC) cells resistant to the kinase inhibitor sorafenib, primarily by upregulating the MAPK pathway." (PMID 39664377, 2024). "Other researchers found that Vitamin K and sorafenib treatment in hepatocellular carcinoma promotes inhibitory MET Y1349 phosphorylation, leading to increased PI3K/AKT signaling and inhibition of RAF." (PMID 39062731, 2024). "In hepatocellular carcinoma, Vitamin K and sorafenib treatment synergistically decreased MET phosphorylation, leading to decreased EMT, proliferation, and migration." (PMID 39062731, 2024). "IQGAP1 knockdown increases HGF-stimulated MET activation and coupling to Akt and ERK in hepatocellular carcinoma cells, indicating that it inhibits MET signaling." (PMID 37071417, 2023). "Consistent with our results, IQGAP1 knockdown in Snu-449 hepatocellular carcinoma cells was recently reported to enhance HGF-stimulated MET activation and phosphorylation of Akt." (PMID 36766826, 2023). "Enhanced activation of the transcription factor MYC and of the receptor tyrosine kinase MET are among the events frequently occurring in hepatocellular carcinoma (HCC)." (PMID 36433941, 2022). "The combination of MET inhibitors and autophagy inhibitors significantly improved the efficacy of hepatocellular carcinoma therapy in mice." (PMID 36505831, 2022). "Strengthening the importance of investigating novel PTMs, recent research identifying a new and critical PTM on FIS1 by MET demonstrates the necessity of this signaling pathway to drive metastatic dissemination in hepatocellular carcinoma." (PMID 35356277, 2022). "SOX13 promotes colorectal cancer metastasis by transactivating SNAI2 and c-MET and regulates cancer stem-like properties and tumorigenicity in hepatocellular carcinoma cells." (PMID 35631574, 2022). "More importantly, introduction of SOX2, AKT or c-MET alleviated lenvatinib sensitivity in MUC15 overexpression hepatoma cells." (PMID 35236826, 2022). "And compared with treatment with MET inhibitor or anti-pd1 alone, the duration of both drugs significantly inhibited hepatocellular carcinoma cell growth and prolonged survival time in mice." (PMID 36176401, 2022). "This open-label, Phase 1b/2 study evaluated the highly selective MET inhibitor tepotinib in systemic anticancer treatment (SACT)-naive Asian patients with advanced hepatocellular carcinoma (aHCC) with MET overexpression." (PMID 33972742, 2021). "In hepatocellular carcinoma, hepatocyte growth factor activates the c-MET and MEK-ERK1/2 pathways, and upregulates the expression of KRT19." (PMID 34659572, 2021). "Although abnormal activation of MET in some cancers, such as hepatocellular carcinoma, is known to be correlated with poor prognosis, the role of the miR-34a-MET axis in HNSCC has not been investigated." (PMID 33596979, 2021). "This Phase 1b/2 study evaluated tepotinib, a highly selective MET inhibitor, in US/European patients with sorafenib pretreated advanced hepatocellular carcinoma (aHCC) with MET overexpression." (PMID 33824476, 2021).
hepatocellular carcinoma (continued). "The authors primarily studied the function of MET, which is an oncogene regulating proliferation, poor prognosis, and poor outcome in human hepatocellular carcinoma." (PMID 32075174, 2020). "c-MET has strong oncogenic properties in hepatocellular carcinoma (HCC), glioblastoma, and other malignancies, c-MET inhibitors were, therefore, suggested for cancer therapy." (PMID 32161259, 2020). "In hepatocellular carcinoma cells, ER stress resulted in a reduction of the protein and phosphorylation levels of p145 MET (c-MET tyrosine kinase B subunit)." (PMID 33023670, 2020). "In contrast, in a separate model of hepatocellular carcinoma, PARP1 phosphorylation was dependent on the nuclear translocation of EGFR and formation of an EGFR/MET heterodimer causing MET activation." (PMID 32722408, 2020). "Hepatocellular carcinoma-derived EVs have been shown to activate the HGF/MET/AKT pathway in sensitive hepatocellular carcinoma cells, thereby inducing sorafenib resistance." (PMID 33080788, 2020). "Overexpression of miR-199a-5p in hepatocellular carcinoma was shown to modulate tumor cells sensitivity to doxorubicin by targeting the MET-oncogene." (PMID 31636666, 2019). "The TTA1 cells also exhibited overexpression of MET protein, compared to the other thyroid carcinoma-derived cells, normal human thyroid tissue and the human hepatocellular carcinoma cell line HEPG2, which served as control for MET expression." (PMID 31040922, 2019). "MACC1 inhibits the cell apoptosis by targeting the HGF/c-MET/PI3K/AKT signaling pathway in hepatocellular carcinoma." (PMID 28348518, 2017). "ARQ 197-215 was a randomized placebo-controlled phase II study testing the MET inhibitor tivantinib in second-line hepatocellular carcinoma (HCC) patients." (PMID 27579536, 2016). "It was shown that HGF, together with its ligand MET (HGF/MET), promotes cell proliferation, survival, migration, and angiogenesis in hepatocellular carcinoma." (PMID 26859576, 2016). "Activation of MEK/ERK and PI3-K/Akt signaling are largely mediated by RTK, in particular EGFR and c-MET, in hepatoma cells." (PMID 25890498, 2015). "Prospective data from studies of tivantinib in the treatment of hepatocellular carcinoma found that positive MET expression (≥2+ staining in ≥50 % of tumor cells by IHC) was associated with improved overall survival (OS), PFS, and time to progression." (PMID 26123926, 2015). "Foretinib, a VEGFR-2 and c-MET inhibitor, has also been shown to induce a G2/M arrest in cells from hepatocellular carcinoma 37 and ovarian cancer." (PMID 24238094, 2014). "Attenuated c-MET expression also weakens the invasiveness and metastasis of colon cancer and hepatocellular carcinoma." (PMID 25009663, 2014). "The present study aims to analyze the molecular signatures of liver cancer in a c-MET-transgenic mouse model and investigate its prognostic relevance to human hepatocellular carcinoma (HCC)." (PMID 21949730, 2011). "The MET and TNFSF10 receptor tyrosine kinases, both highly expressed in subtype 2, were closely associated with the proliferation, survival, invasion, and metastasis of hepatocellular carcinoma cells." (PMID 39944086, 2025). "The results of target prediction showed that PDGFRA, FLT1, PIK3CD and MET might be the main targets of compound 15 against hepatocellular carcinoma." (PMID 41023382, 2025). "Additionally, C1GALT1 has been shown to modify O‐glycosylation of receptor tyrosine kinases, such as MET with the enhancement of HGF‐induced activation in hepatocellular carcinoma." (PMID 39844613, 2025). "A preliminary study on hepatocellular carcinoma showed that the focal adhesion kinase protein (FAK) might be a regulator of the drug response to anti-MET therapy." (PMID 36982721, 2023). "Furthermore, the small molecular inhibitors tivantinib and tepotinib have been investigated in patients with hepatocellular carcinoma using MET IHC2+ and IHC3+ overexpression for enrollment in the clinical trials." (PMID 35565287, 2022).
hepatocellular carcinoma (continued). "Besides being investigated for treatment of NSCLC, MET inhibitors are under clinical development for different indications, such as gastric and gastroesophageal cancer, hepatocellular carcinoma, and renal cell carcinoma." (PMID 35565287, 2022). "Importantly, MUC15/c-MET/PI3K/AKT/SOX2 axis determines the responses of hepatoma cells to lenvatinib treatment, and MUC15 overexpression abrogated lenvatinib resistance." (PMID 35236826, 2022). "Tyrosine kinase MET is considered an excellent target for hepatocellular carcinoma treatment." (PMID 36176401, 2022). "Moreover, by sequestering hsa-miR-335-5p, NEAT1 induces AKT phosphorylation and c-MET expression in hepatocellular carcinoma cells." (PMID 35008626, 2021). "C1GALT1 modified the O-glycosylation of MET in hepatocellular carcinoma." (PMID 34452648, 2021). "Previous studies have demonstrated that the inhibition of HDAC could reduce the expression of c-MET and the phosphorylation of extracellular signal-regulated kinases 1 and 2 by decreasing the levels of hsa-miR-449a in hepatocellular carcinoma cells." (PMID 32792859, 2020). "Furthermore, a heterodimer of EGFR and MET can phosphorylate Y907 of PARP1 in the nucleus of hepatocellular carcinoma and contribute to this resistance." (PMID 32093123, 2020). "And, MET may serve a role in regulating PD-L1 expression in hepatocellular carcinoma Meanwhile, MET is also involved in high-risk metastasis progression in thyroid cancer." (PMID 32714651, 2020). "Since NRF2 is found to be upregulated in both colorectal and hepatocellular carcinoma and miR-1 is inhibited then this forms the hypothesis that NRF2 could be linked to high c-MET expression in these diseases." (PMID 24029073, 2013). "The c-MET signalling pathway is upregulated in both hepatocellular carcinoma and colorectal cancer." (PMID 24029073, 2013). "MET gene amplification, which leads to a constitutively active receptor due to overexpression, has been identified in patients with gastric cancers, lung tumors, renal cell carcinomas, hepatocellular carcinomas, ovarian tumors, melanomas, and triple-negative breast cancer (TNBC)." (PMID 39598385, 2024). "Aberrant activation of c-MET can lead to tumor progression, invasive growth, angiogenesis, metastasis, and resistance to therapies, and plays a vital role in the treatment of tumors, especially hepatocellular carcinoma; therefore, c-MET has become a popular target for tumor treatment." (PMID 37175820, 2023). "However, c-MET was reduced in MUC15 overexpression hepatoma spheroids." (PMID 35236826, 2022). "In conclusion, the present study highlighted the critical roles of MET, TIMP1, and VTN in the progression of MVI in hepatocellular carcinoma, underscoring their previously unreported contributions to this process." (PMID 39944086, 2025). "Previous reports have shown that USP33 promotes metastasis in hepatocellular carcinoma by deubiquitinating transcription factor (SP1) and upregulating cell-surface receptor c-mesenchymal–epithelial transition factor (c-MET) expression." (PMID 40695806, 2025). "In hepatocellular carcinoma (HCC), sorafenib resistance is induced by the delivery of hepatocyte growth factor (HGF) through EVs, which activates the HGF/c-MET/PI3K/AKT signaling pathway." (PMID 40475777, 2025).